CA9 (carbonic anhydrase 9)
Diseases named in the same sentence as CA9 in open-access papers (continued):
Sharing a sentence is not in itself a finding about the gene and the disease.
colon carcinoma (continued). "More recently, the Spidel team has generated two optimized scFv-auristatin F conjugates with a DAR of 2, targeting CA9, exhibiting similar efficacy with an EC50 of 0.57 and 0.81 nM on colon cancer cells HT116- CA9." (PMID 32937862, 2020). "The immunohistochemical staining was conducted for CA9 and HIF-1α to verify their protein expressions within the normal and colon tumor tissues." (PMID 26447758, 2015). "Recently, it has been suggested that beta-catenin promotes CA9 expression, by acting as HIF-1alpha transcriptional co-factor in colon cancer cells." (PMID 24260469, 2013). "Molecular docking analysis confirmed that formononetin could strongly interact with CA9 and MME, indicating their critical roles in formononetin’s suppression of colon cancer cells." (PMID 41567641, 2025). "When exploring tumor databases, we demonstrated that colon tumors exhibit distinct levels of macrophage infiltration, where the most infiltrated tumors are also the most hypoxic ones, presenting higher levels of HIF1A, CA9, and LOX expression." (PMID 32231135, 2020). "Carbonic anhydrase 9 is predominantly regulated by HIF-1 (not HIF-2) activity, but does not significantly associate with HIF-1α expression in colon cancer." (PMID 19844231, 2009).
prostate carcinoma (35 papers, 2012 to 2025). A carcinoma that arises from epithelial cells of the prostate gland. "There was limited overlap of the biomarkers in prostate cancer (only IL-8 was elevated) and kidney cancer (only CA9 and VEGF were elevated)." (PMID 29467953, 2018). "Although we observed an overrepresentation of CAIX positive immunoreactivity in prostate carcinoma compared to BPH, the nonsynonymous SNP in CA9 + 201 were unable to explain variations in the levels of CAIX protein expression in the prostatic tissue." (PMID 28143503, 2017). "During hypoxia, STAT3 and HIF-1α cooperatively activate HIF-1α target genes, VEGF, phosphoglycerate kinase 1 (PGK1), and carbonic anhydrase 9 (CA9) in prostate cancer cells." (PMID 28978186, 2017). "However, in the case of CA9, its expression in prostate cancer is inconsistent; CA9 is highly expressed in androgen-independent prostate cancer cell lines in hypoxia, but absent or moderate in primary prostate cancer and benign prostatic hypertrophy (BPH)." (PMID 35328229, 2022). "Based on the role of hypoxia-associated molecules in cancer cell biological behaviour and clinical outcome, we assumed there might be an association, at the genetic and protein level, between HIF1A, LOX, CA9 and KDR genetic variants, the protein expression and prostate carcinoma." (PMID 28143503, 2017). "The genotypic distributions for the putative functional target SNPs in HIF1A, LOX, CA9 and KDR were similar between nodular prostate hyperplasia and prostate carcinomas." (PMID 28143503, 2017).
lymph node metastasis (30 papers, 2005 to 2025). "In the group of 122 patients who were CA9-positive, a significant association was also revealed between pathological lymph-node metastasis and [18F]FDG PET/CT accumulation." (PMID 39471162, 2024). "Our previous research showed that carbonic anhydrate 9 (CA9) polymorphism is associated with a 4.5-fold increased risk of lymph node metastasis while growth arrest-specific 5 (GAS5) SNPs play a protective role in nodal invasion (OR 0.545, p = 0.043)." (PMID 34574033, 2021). "Also, the risk of lymph node metastasis of lung adenocarcinoma was lower likely with the CA9 SNP rs2071676 AG + GG in the EGFR wild type group (p = 0.005)." (PMID 32365566, 2020). "Furthermore, the CA9 SNP rs2071676 is correlated to lower tumor stage and lower risk for developing lymph node metastasis in lung adenocarcinoma, mainly in the EGFR wild type." (PMID 32365566, 2020). "This current study also revealed that amplification of 9p was significantly associated with lymph node metastasis that might be driven by proto-oncogenes such as CA9, VCP, DCTN3, and STOML2." (PMID 28384287, 2017). "In the present investigation, the respective sensitivity and specificity values of [18F]FDG PET/CT for detecting lymph-node metastasis were 57% and 93% in 224 adenocarcinomas but low at only 36% and 69% in the CA9-positive SCC cases." (PMID 39471162, 2024). "The CCRCC cases were in pT1 stage; 6 exhibited cup-shaped staining of CA9, and 1 displayed lymph node metastasis at the time of surgery." (PMID 31656019, 2020). "The CA9 expression in CNB specimens was significantly correlated with lymph node metastasis (70%, p = 0.001) and lymphatic invasion (69%, p = 0.003)." (PMID 24893880, 2014). "It was reported that high expression of CA9 was more frequent with lymph-node metastasis in several kinds of solid tumors including oral cancer." (PMID 23226559, 2012). "In lymph node metastases, 21.7, 66.7 and 26.7% were positive for, respectively, CA9, DEC-1 and Hif-1α." (PMID 16251878, 2005). "In the CA9-negative group, there was a significant association between pathological lymph-node metastasis and [18F]FDG PET/CT accumulation in all 216 patients." (PMID 39471162, 2024). "Furthermore, when two lymph node metastases from the same patient were compared, a perfect correlation was found for CA9 expression (P<0.001)." (PMID 16251878, 2005). "The CA9 expression in CNB specimens was significantly correlated with pathological response, lymph node metastasis, and lymph-vascular invasion." (PMID 24893880, 2014). "There appears to be no published report of a correlation between CA9 expression and lymph-node metastasis in NSCLC, however." (PMID 39471162, 2024). "In this study, the correlation between the CA9 expression for lymph-node metastases in NSCLC and [18F]FDG PET/CT results was investigated in order to clarify the efficacy of [18F]FDG PET/CT for detecting lymph-node metastases of NSCLC patients." (PMID 39471162, 2024).
pancreatic cancer (29 papers, 2011 to 2024). "The expression levels of ENO1 in human pancreatic cancer are closely associated with those of the hypoxia marker CA9 as well as nerve and vascular invasion, thus suggesting that ENO1 promotes the invasion and metastasis of pancreatic cancer, in agreement with the results of many in vitro studies." (PMID 36476328, 2022). "The differential expression analysis of the TCGA data grouped by the level of CD8+ T cell infiltration indicates that the expression of carbonic anhydrase 9 (CA9) is the most significant, and the survival analysis suggests that CA9 is associated with the overall survival of pancreatic cancer." (PMID 35155218, 2021). "Given the reported involvement of IL-6 in upregulation of CAIX expression in multiple previously-mentioned cancer models, it seems plausible that IL-6 signaling could also be implicated in the transcriptional regulation of CA9 in precursor lesions as well as in primary pancreatic tumors." (PMID 32707920, 2020). "More CA9-positive pancreatic cancers were found in the high ENO1 expression group than the low ENO1 expression group." (PMID 36476328, 2022). "Patients with pancreatic cancer with high CA9 expression had poor overall survival (χ2 = 5.005, P = 0.025)." (PMID 36476328, 2022). "ENO1 was expressed mainly in the cytoplasm and nuclei of pancreatic cancer cells, whereas CA9 was expressed in the cell membrane." (PMID 36476328, 2022). "Indirect co-culture model of human pancreatic cancer cell lines and healthy individual-derived PBMCs were used to determine the effect of CA9-related Acidic Microenvironment on CD8+ T cells." (PMID 35155218, 2021). "Compared with normal tissues and precancerous lesions, CA9 expression is higher in pancreatic cancer tissues, and it is positively correlated with tumor size and stage." (PMID 35155218, 2021). "The results showed that CA9 is widely expressed in pancreatic cancer cell lines, such as PANC-1, CFPAC-1, MIA Paca-2, etc." (PMID 35155218, 2021). "Although several studies have been interested in the immunohistochemical staining of CAIX within pancreatic tumors, very little is known about the transcriptional regulation of CA9." (PMID 32707920, 2020). "Our Genevestigator analysis also showed an increased CA9 level in samples of intraductal papillary mucinous adenoma, adenocarcinoma, and invasive carcinoma from patients with pancreatic cancer compared to normal pancreatic duct tissue." (PMID 32707920, 2020). "They showed that hypomethylation of MUC1 and MUC4 promoters correlates with mRNA and IHC positivity of both mucins in pancreatic cancer tissues, and with a high CA9 level." (PMID 32707920, 2020). "We also compared the induction of CA9 in pancreatic cancer cells grown in monolayer versus 3D tumor spheroids." (PMID 30214007, 2018). "CA9 inhibitor SLC-0111 increased the pH value in the pancreatic cancer cell culture supernatant." (PMID 35155218, 2021). "We further evaluated the effect of CA9 on CD8+ T cells in pancreatic cancer at the cellular level." (PMID 35155218, 2021). "It was shown that CA9 is mainly expressed in pancreatic cancer cell cluster." (PMID 35155218, 2021). "Several experimental studies have shown that the hypoxia-induced miR-210 increases the expression of hypoxia-induced downstream targets VEGF and CAIX (carbonic anhydrase 9) in pancreatic cancer cells by a HIF-1α-dependent mechanism, suggesting a regulatory role in tumor angiogenesis." (PMID 22952749, 2012). "Pancreatic cancer single-cell sequencing data set PAAD_CRA001160 analysis results show that CA9 is mainly expressed in pancreatic cancer cell clusters, and the expression of the cancer cell subgroup CA9 in the single-cell data set is correlated with CD8+ T cell infiltration." (PMID 35155218, 2021). "Pancreatic cancer cells may inhibit the infiltration of CD8+ T cells through CA9." (PMID 35155218, 2021).
pancreatic cancer (continued). "Based on multiple evidence (expanded upon in Section 2, which discusses transcriptional regulation of CA9 in pancreatic tumors), high CAIX-positivity within IPMN could be affected by the activity of several signaling pathways relevant to the microenvironment of precursor lesions." (PMID 32707920, 2020). "To further study if it was the effluxed lactate in the pancreatic tumor that contributed to the increased CD8 + infiltration, we next implanted KPC:CAF cells in the pancreas of C57BL6 animals and treated them with a CA9 inhibitor." (PMID 33177492, 2020). "To study if inhibition of lactate efflux affected the response of pancreatic tumors to anti-PD1 therapy, we next evaluated the effect of CA9 inhibitor in combination with anti-PD1 therapy." (PMID 33177492, 2020).
invasive breast carcinoma (26 papers, 2003 to 2025). A carcinoma that infiltrates the breast parenchyma. "Hypoxia-regulated CA9 expression is associated with poor survival in patients with invasive breast cancer." (PMID 27478411, 2016). "Here, we are the first to show that CA9 expression as measured by real-time RT–PCR is related to poor outcome after adjuvant treatment in unilateral, invasive breast cancer." (PMID 12865916, 2003). "In addition, hypoxia up-regulated surface antigens like glucose transporter 1 (GLUT1) and carbonic anhydrase 9 (CAIX) that are expressed in about half of invasive breast cancers and also in DCIS and therefore might be valuable targets." (PMID 22695343, 2012). "Compared with pure DCIS samples, the degree of CA9+ epithelial cell and FOXP3+ lymphocyte colocalization was significantly higher in the invasive compartment of invasive breast cancer (IDC), but significantly lower in the synchronous DCIS compartment." (PMID 36109587, 2022).
gastric cancer (25 papers, 2007 to 2025). A primary or metastatic malignant neoplasm involving the stomach. "Nevertheless, high Ca9 expression is a characteristic of healthy cells, and its loss is a frequent acquired feature of gastric cancer cells." (PMID 40227324, 2025). "Similarly the HIF-1α regulated CA9 was expressed at the invasive tumour edge in a subset of gastric cancer where it was associated with tumour invasion, advanced disease and a poor prognosis." (PMID 17179985, 2007). "It has been reported that DNA methylation predominantly regulated CA9 expression in gastric cancer, while histone modifications, mediated by MORC2 and HDAC4, have been documented to control CA9 transcriptional activation through histone H3 deacetylation." (PMID 38177154, 2024). "Although this family of enzymes are ubiquitously expressed in humans, CA9 is restricted mainly to the gastrointestinal tract further upregulation is seen in gastric cancer and several other solid tumors." (PMID 33007872, 2020). "Carbonic anhydrase 9 (CA9) plays a role in the metabolism of carbon and has also been associated with hypoxia and proliferation in different cancers such as gastric cancer." (PMID 31565069, 2019). "CREB has been shown to inhibit the transcription of CA9 in gastric cancer." (PMID 40227324, 2025). "Interestingly, CREB is known to be a key negative regulator of carbonic anhydrase IX (CA9), which is downregulated in gastric cancer." (PMID 39171503, 2024). "In addition, some studies have reported that a subgroup of gastric cancers retains CA9 expression in cancer cells at the invasion front and that expression of CA9 is associated with increased invasion." (PMID 27478411, 2016). "This is consistent with the observation that Ca9 expression was frequently lost in gastric cancers in part by methylation, while contradictory to another report that the activity of Ca9 contributes to invasion and thus advanced tumor progression in a subset of gastric cancers." (PMID 29745833, 2018).
triple-negative breast carcinoma (24 papers, 2013 to 2026). An invasive breast carcinoma which is negative for expression of estrogen receptor (ER), progesterone receptor (PR), and human epidermal growth factor receptor 2 (HER2). "CA9 might be a useful biomarker for chemotherapy in triple-negative breast cancer." (PMID 24893880, 2014). "Increases in VEGF and CA9 and decreases in VEGFR2 with cabozantinib treatment have been observed in triple negative breast cancer, and increases in VEGF, CA9, MET, and IL-8 and decreases in VEGFR2 with cabozantinib treatment have been observed in castration-resistant prostate cancer." (PMID 34364385, 2021). "To conduct these studies, we first coupled biotin ligase (BirA*) to the C-terminus of full length, wild-type (WT) human CA9 and expressed the CAIX-BirA* fusion protein constitutively in WT MDA-MB-231 human triple negative breast cancer cells (MDA-MB-231-CAIX-BirA*)." (PMID 28692057, 2017). "The chemosensitivity of triple-negative breast cancer patients with CA9 was significantly lower than that of the CA9-negative cases." (PMID 24893880, 2014). "Since that CA9 knockdown halts MDA-MB-231 xenografts, the available data agree on the crucial role of the beta-catenin-dependent CA9 and SNAI2 mRNA stability and expression in the biology of basal-like/triple-negative breast cancer." (PMID 24260469, 2013). "In our present analysis of 31 triple-negative breast cancers, the DFS of patients with CA9-positive tumors was significantly shorter (p = 0.015) than that of patients with CA9-negative tumors." (PMID 24893880, 2014).
head and neck cancer (22 papers, 2010 to 2025). A primary or metastatic malignant neoplasm affecting the head and neck. "CA9 also links to poor vascularization and resistance of chemoradiotherapy in head and neck cancer and is associated with reduced overall survival and disease-free survival." (PMID 24349364, 2013). "The strongest effect of ascorbate dependent downregulation of HIF-1α target genes expression was also observed for CA9 in head and neck carcinoma cell line 22B (more than 75-fold decrease in CA9 compared to a 25-fold decrease for GLUT3 and a 50-fold decrease for MMP-2)." (PMID 29100428, 2017). "Hypoxia is a common factor in head and neck cancers and shows a cascade of response with intermediate biomarkers like HIF-1, HIF2, GLUT, and CA-9." (PMID 38200568, 2024). "As tumor hypoxia is the largest determinant in treatment-efficacy variability in survival in head and neck cancers many endogenous markers such as HIF1A/HIF1α, CA9/CAIX, SLC2A1/GLUT1, have been investigated." (PMID 34904929, 2022). "As tumor hypoxia is the largest determinant in treatment-efficacy variability in survival in head and neck cancers many endogenous markers such as HIF1A, CA9, SLC2A1 and others, have been investigated." (PMID 34904929, 2022). "We also performed correlation analysis based on TCGA data from colon and head and neck carcinoma provided in UCSC Xena which confirmed that CA9 and PTGS2 expression does not correlate (correlation coefficient -0.004 and 0.04 for COAD and HNSC, respectively)." (PMID 40408503, 2025).
hepatocellular carcinoma (19 papers, 2015 to 2025). A malignant tumor that arises from hepatocytes. "Moreover, the presence of CA9 single nucleotide polymorphism (SNP) was associated with the development of uterine cancer, urothelial cell carcinoma, colorectal carcinoma hepatocellular carcinoma, and oral cancer." (PMID 32365566, 2020). "HIF1A and CA9 were activated in TGFβ‐induced hepatoma cell line MHCC‐97H and were inhibited by sanguinarine." (PMID 40417738, 2025). "For instance, recent studies have identified miRNA binding site polymorphisms in genes implicated in migration, invasion, and angiogenesis, such as RASA1, COL1A2, CA9, CD147, VHL, and RYR3, which can influence susceptibility to hepatocellular carcinoma (HCC)." (PMID 41409896, 2025). "The authors suggested CA9 as a potential marker for the differentiation of cholangiocellular carcinoma (CCA) and hepatocellular carcinoma as 90% of CCA showed a strong CA9 expression." (PMID 30011326, 2018). "Carbonic anhydrase IX (CA9) expression level has been considered as a poor prognostic factor in hepatocellular carcinoma (HCC) patients." (PMID 28667334, 2017). "In primary hepatocellular carcinoma, lncRNA-LET expression is inversely correlated with the prototypical hypoxia marker carbonic anhydrase 9, and experimentally, lncRNA-LET downregulation leads to hypoxia-induced cancer cell invasion in hepatocellular carcinoma cells." (PMID 28793797, 2018).
kidney cancer (19 papers, 2009 to 2026). Primary or metastatic malignant neoplasm involving the kidney. "We first considered RCC, an adult kidney cancer where the cancer cell transcriptome can be definitively identified based on the tumour marker CA9, caused by the near universal disruption of the VHL gene underpinning RCC11." (PMID 36071103, 2022). "CA9 can be used to predict clinical outcome in such high risk kidney cancer patients who need adjuvant immunotherapy and CA9 targeted therapies." (PMID 24349364, 2013). "hMOF as an acetyltransferase of H4K16 might be involved in the pathogenesis of kidney cancer, and this epigenetic changes might be a new CA9-independent RCC diagnostic maker." (PMID 23394073, 2013). "For instance, it is known that kidney cancer cells overexpress Ca9 and that kidney cancer patients have higher levels of Ca9-overexpressing lEVs than patients without cancer." (PMID 36975533, 2023). "As previously reported, elevated Ndufa4l2 and Carbonic Anhydrase 9 (Car9) transcript levels are recapitulated in our TRACK (HIF1α) kidney cancer mouse model relative to normal kidney (WT)." (PMID 34970493, 2021). "All primary cultures showed kidney cancer markers such as CA9, Pax8, CD10 or MIF1a." (PMID 36975533, 2023).